XPO1 (exportin 1)
Diseases named in the same sentence as XPO1 in open-access papers (continued):
Sharing a sentence is not in itself a finding about the gene and the disease.
cancer (continued). "In this context, exportin 1 (XPO1), the sole nuclear exporter for a variety of tumor suppressors, cell cycle regulators and growth promoting/anti-apoptotic proteins, was found to be over-expressed in several cancer types, including BC." (PMID 34072442, 2021). "The effect of selinexor or XPO1 inhibition on cancer cell sensitivity to NK cell activity however has not previously been investigated." (PMID 34926302, 2021). "Leptomycin B (LMB) is a prototypical inhibitor of XPO1 and covalently binds to Cys528 located in the NES binding groove of XPO1, and has been studied as a potent agent against various types of cancer as well as an antiviral agent for many years." (PMID 34012430, 2021). "Previous studies in cancer cells have shown treatment with SINE compounds do not induce apoptosis as a consequence of XPO1 inhibition." (PMID 34584169, 2021). "Recently, selective inhibition of nuclear export by the second-generation exportin-1 (XPO1) inhibitor KPT-8602 (eltanexor) was shown to induce apoptosis in various cancer types, including ALL, without deleterious effects to normal hematopoiesis." (PMID 34167562, 2021). "Compared with normal liver tissues, XPO1 mRNA levels exhibited a 1.642-fold (Roessler liver dataset, P=2.27e-09), 1.683-fold (Roessler liver 2 dataset, P=9.79e-54) and 1.782-fold (Wurmbach liver dataset, P=2.65e-07) increase in HCC cancer tissues." (PMID 31371628, 2019). "On the other hand, inhibition of XPO1 by RNA interference or with inhibitors, such as leptomycin B or selective inhibitors of nuclear export (SINE), prevents cellular transformation and tumorigenesis in numerous cancer models." (PMID 31088931, 2019). "Furthermore, we demonstrated the anti-proliferative effect of XPO1 inhibitor, KPT-330, on HT29 colrectal cancer cell line." (PMID 31870117, 2019). "Retrospectively, we analyzed XPO1 mRNA expression in 741 pancreatic samples, including 95 normal, 73 metastatic and 573 primary cancers samples, and searched for correlations with clinicopathological and molecular data, including overall survival." (PMID 31052304, 2019). "Exportin1 (XPO1, also known as chromosomal maintenance region 1, or CRM1) mediates nuclear export of proteins and RNAs, and ribosome biogenesis, which are important for cancer growth and survival." (PMID 31113936, 2019). "Similar to LMB, CBS9106 blocks XPO1 export function by binding to the cys528 amino acid in the NES recognizing domain, retains TSPs in the nucleus and induces cell cycle arrest and apoptosis in cancer cells." (PMID 29735942, 2018). "We conducted a literature search to present the recent major publications establishing the landscape of XPO1 molecular alterations, their impact on the XPO1 protein, their interest as biomarkers, and investigations into the development of new SINE therapies in B cell hematological malignancies." (PMID 28196522, 2017). "Integrating these three complementary and orthogonal methods, we identify CDK4 and XPO1 as potential therapeutic targets in this cancer, which has no known alterations in these genes." (PMID 27329820, 2016). "However, in PDAC and other cancers, aberrant over-expression of nuclear exporter protein CRM1/Exportin 1/Xpo1 results in mis-localization of TSPs thereby inhibiting their cell surveillance activity." (PMID 24899509, 2014). "Collectively, these data indicate that XPO1 is a critical regulator of the TME, and its pharmacologic inhibition may represent a promising strategy to enhance anti-tumor immunity and improve the efficacy of cancer therapies." (PMID 41440011, 2025). "Hence, XPO1 is essential and MYC synthetic lethal in vitro in multiple types of MYC-driven cancer." (PMID 38302473, 2024). "KPT-330 is a potent nonreversible Xpo1 inhibitor currently in clinical trials in cancer therapy." (PMID 37175668, 2023).
cancer (continued). "Although these drugs have not been examined in-depth as cancer treatments, their ability to modulate nuclear localization prompted researchers to investigate the effects of combining XPO1 inhibitors with choline salicylate (CH), a drug commonly used to treat rheumatoid arthritis." (PMID 36671496, 2023). "This proposition was validated when we generated two KRAS G12C inhibitor–resistant cancer cell lines from KRAS G12C–mutant parental cells (MiaPaCa-2) and found that both AMG510- and MRTX1257-resistant cell lines were indeed sensitive to the XPO1 inhibitor selinexor." (PMID 35573474, 2022). "HHIPL2, XPO1, SALRNA1, ZBTB45, ANP32AP1, ACTR3BP5, LOC100129138, GPR45, and CAB39L gene deletions were associated with non-cancer subjects without FCH (p < 0.05), while RAB9BP1, LOC101928523, and MALRD1 gene deletions were related to non-cancer patients with FCH (p < 0.05)." (PMID 33431054, 2021). "In the current study, we noticed a significant apparent of XPO1 overexpression in CRC tumor cells compared to the adjacent normal epithelium as it was reported in many other types of cancers such as esophageal, gastric, lung, and ovarian cancers, as well as leukemic cells." (PMID 31870117, 2019). "The XPO1 overexpression process in cancer cells is not currently clearly known." (PMID 28196522, 2017). "Therefore, a combination therapy involving XPO1 and KRAS G12C inhibitors can be a viable option, especially considering that preclinical and clinical studies have already reported the emergence of resistant subpopulations of cancer cells in response to KRAS G12C inhibitor monotherapy." (PMID 35573474, 2022). "Due to variations between datasets, FABP4 expression did not predict patient disease-free survival in the TCGA Firehose Legacy dataset, while U2AF2, RUVBL1, XPO1, and POSTN did not predict disease-free survival in the BS Taylor, Cancer Cell, 2010 dataset." (PMID 39402324, 2024). "As a negative control, the XPO1 occupancy assay was also performed with KPT-301, the inactive, trans isomer of KPT-185, that does not have anti-cancer activity." (PMID 26654943, 2016). "An in-depth investigation into XPO1 expression in wide-ranging, solid and haematological cancer types found negative correlations between XPO1 expression and immune scores as calculated using the ESTIMATE (estimation of stromal and immune cells in malignant tumour tissues) algorithm." (PMID 40291981, 2025). "Furthermore, PKF050-638 is a XPO1-inhibitor used in HIV treatment to inhibit the nuclear export of HIV-1 Rev protein; however, its anti-cancer effect has not been investigated yet." (PMID 38938904, 2022).
tumor (227 papers, 2010 to 2025). "Mutations leading to truncated SMARCB1 can result in its exportin-1-mediated mislocalisation in the cytoplasm and hence loss of tumour-suppressive capacity." (PMID 40422882, 2025). "We discovered that expression of the gene encoding the nuclear export protein XPO1, which shuttles eIF4E to the cytoplasm, was substantially elevated in NB tumor cell populations and that upregulated XPO1 expression correlated with poor patient survival." (PMID 41279557, 2025). "While XPO1 mutations are relatively rare, their presence correlates with poor prognosis and higher tumor mutational burden, highlighting their potential as prognostic biomarkers." (PMID 41440011, 2025). "Our analysis of the key TFs driving the distinct functions of these clusters revealed that the ten most active transcription factors in XPO1+Epithelial were predominantly associated with tumor proliferation, migration, and invasion." (PMID 39712016, 2024). "While it was previously reported that XPO1 was aberrantly elevated in HCC and promoted tumor cell growth, the mechanisms underlying the function and regulation of XPO1 in HCC remain to be fully elucidated." (PMID 37497004, 2023). "XPO1 expression has also shown to be associated with tumour size, lymph node invasion, and liver metastasis and can act as a prognostic marker." (PMID 38131168, 2023). "The most prominent example is overexpression or mutation of XPO1, which localizes many tumor suppressors to the cytoplasm to render them inactive." (PMID 37945593, 2023). "Previously, we found that the dysregulated exportin-1 (also known as CRM1) is mainly responsible for tumor cells to evade apoptosis and promote tumor-associated pathways such as NF-κB signaling." (PMID 37888961, 2023). "Retrospective trial data suggest that tumor cells pretreated with XPO1 inhibitors are more susceptible to T-cell killing." (PMID 37954586, 2023). "In 5 patients, XPO1 mutation was detectable only in the tumor biopsy, but 8 patients had XPO1 mutation detectable only by cfDNA (29% of all XPO1 mutations)." (PMID 36074181, 2022). "Exportin 1 (XPO-1) has a putative oncogenic function by exporting tumor suppressor proteins in different tumor entities and is associated with DH- and TH-DLBCL as well as impaired OS rates in DLBCL." (PMID 35326604, 2022). "Hotspot mutations in XPO1 have been described in several tumor types, including B-cell malignancies, and are reportedly associated with tumorigenesis." (PMID 35347147, 2022). "We further analyzed the association between the circXPO1 level and XPO1 gene copy number in LUAD tumor tissues." (PMID 33268793, 2020). "Although the XPO1 overexpression was strongly associated with high Ki67 expression (P=0.001), only Ki67 expression showed significant association with tumor size (P=0.012)." (PMID 31870117, 2019). "In this study we identified a high tendency of XPO1 overexpression in moderately/poorly differentiated tumors and was significantly associated with advanced tumor stage (III/IV) (P=0.059 and P=0.049, respectively)." (PMID 31870117, 2019). "Regarding to the histopathological characteristics, the XPO1 overexpression significantly associated with advanced tumor stages (P=0.049) and has great tendency towards moderate/poorly differentiated tumors." (PMID 31870117, 2019). "Similarly, the XPO1 E571 mutation was detected in plasma cell‐free DNA from Hodgkin's lymphoma patients and was associated with tumour regression or progression." (PMID 38783482, 2024).
tumor (continued). "Thus, overexpression of XPO1 is associated with poor prognosis and drug resistance in various tumours, including osteosarcoma, glioma, pancreatic cancer and ovarian carcinoma." (PMID 37601856, 2023). "XPO1 aberration leads to the functional inactivation of tumor suppressor proteins through exportation from the nucleus to the cytoplasm via the nuclear pore complex, which is implicated in tumorigenesis in various tumor types." (PMID 37422534, 2023). "In regards to circulating tumor DNA (ctDNA), retrospective analyses have identified mutations such as XPO1 E571K that are present in the tumor and plasma and could become a useful genetic biomarker at diagnosis and for minimal residual disease (MRD) detection." (PMID 35884585, 2022). "Further characterization of these interactions will be necessary to fully describe the altered molecular pathways stemming from E571 XPO1 mutations that may influence the sensitivity and cytotoxic efficacy of tumor cells to inhibition by SINE molecules." (PMID 33451349, 2021). "Significantly, we found a strong concordance between the XPO1 overexpression and high Ki67 expression in the tumor cells within the most tissue sections that showed immunoreactivity for both XPO1 and Ki67, and the XPO1 overexpression was strongly associated with the high Ki67 expression (P=0.001)." (PMID 31870117, 2019). "We propose that co-targeting ER and XPO1 is an improved therapeutic strategy because inhibiting the proteins in combination caused both a metabolic shift and induced autophagy, which together led to prolonged tumor regression." (PMID 30987380, 2019). "These correlations explain, at least in part, the oncogenic effect of XPO1 and the association with tumor stage (higher in metastatic samples than in primary tumors, and higher in primary tumors than in normal tissue), with shorter survival and with resistance to cytotoxic therapies." (PMID 31052304, 2019). "Emerging evidence suggests that the mutant XPO1 E571K plays a role in carcinogenesis, and this variant is quantifiable in tumor and plasma cell-free DNA of patients using highly sensitive molecular biology techniques, such as digital PCR and next-generation sequencing." (PMID 28196522, 2017). "Moreover, the XPO1-mutated tumor also showed upregulated protein levels compared with the matched adjacent normal esophageal epithelium, indicating a gain-of-function phenotype." (PMID 28196522, 2017). "Together, this supports a hypothesis in which XPO-1 inhibition leads to a loss of survivin levels, thus inhibiting tumor growth and enhanced apoptosis." (PMID 29340049, 2017). "Functional enrichment analysis revealed that XPO1+Epithelial was predominantly associated with the acute inflammatory response, cell growth, positive regulation of angiogenesis, and epithelial cell proliferation, indicating its potential role in tumor progression." (PMID 39712016, 2024). "The first clinically utilized XPO1 inhibitor (XPO1i) is the anti-tumour Streptomyces antibiotic leptomycin B (LMB), which is a natural XPO1i that covalently attaches to the cargo binding pocket of XPO1 to potently inhibit its interaction with cargo proteins." (PMID 40291981, 2025). "Consistently, in vivo animal experimental results also showed that KLF5 promotes tumor growth through XPO1, at least in part." (PMID 39888288, 2025). "XPO1 dysregulation has been demonstrated in multiple human neoplasms and presents a potentially valuable target for therapy in canine cancers, including canine OS." (PMID 41106249, 2025). "Further studies are warranted to fully elucidate the mechanisms by which XPO1 regulates immunity in different cellular and tumor contexts." (PMID 41440011, 2025). "Following this, a plethora of synthetic XPO1i compounds were developed with potent anti-tumour effects but with tolerable/manageable in vivo toxicity due to the reversible nature of XPO1 inhibition." (PMID 40291981, 2025).
tumor (continued). "Selective inhibitors of nuclear export (XPO1 inhibitors) block the transport of proteins leading to the accumulation and “re‐activation” of tumor suppressor proteins within the nucleus." (PMID 39945382, 2025). "It is widely recognized that the anti-tumor effects of SEL primarily depend on altering the nucleocytoplasmic localization of specific functional molecules transported by XPO1." (PMID 40229499, 2025). "Nuclear export protein 1 (XPO1) is a key nucleoplasmic transporter protein in cells that binds proteins, many of which are tumour suppressor proteins, or RNAs containing hydrophobic nuclear export signals (NESs)." (PMID 40375183, 2025). "XPO1's role extends beyond mere transport; it also inhibits immune responses, thereby facilitating tumor progression." (PMID 39882192, 2025). "It has been reported that XPO1 also influences the tumor microenvironment (TME) by regulating the localization and activity of signaling proteins and cytokine modulators." (PMID 41440011, 2025). "Because tumours depend on the function and expression levels of XPO1 for survival and proliferation, selective inhibitors of XPO1 have been developed." (PMID 40291981, 2025). "Due to its role in various malignancies, XPO1 has become a promising therapeutic target to prevent tumor progression and relapse, and SINE compounds have been developed." (PMID 41440011, 2025). "Dual inhibition of eIF4A and XPO1 synergistically halted tumor growth and prolonged survival in xenograft models." (PMID 41279557, 2025). "These agents included the XPO1 inhibitor, eltanexor, and the KRAS G12D specific inhibitor MRTX-1133 which had activity in tumor lines harboring the KRAS G12D mutation." (PMID 40470182, 2025). "This work demonstrates that XPO1 inhibitor KPT‐330 in combination with CDK4/6 inhibitor additively suppressed BLBC tumor growth in vivo." (PMID 39888288, 2025). "This study and others highlight the impact XPO1 overexpression and inhibition has on the tumor microenvironment." (PMID 40601866, 2025). "Preclinically, Selinexor (SEL) led to tumor growth inhibition by blocking the XPO1‐mediated nuclear transport." (PMID 39945382, 2025). "XPO1 was mainly expressed in the tumor cell region and had higher expression levels in the infiltration regions of tumor cells and other immune and stromal components." (PMID 39882192, 2025). "XPO1 is a central regulator of nucleocytoplasmic trafficking, controlling the localization and function of key tumor suppressors, oncogenes, and RNAs." (PMID 41440011, 2025). "Recent studies have highlighted the potential of XPO1 inhibitors in targeting these pathways to induce apoptosis and inhibit tumor growth." (PMID 40872651, 2025). "Next, we analyzed the expression level of XPO1 and its relationship with tumor microenvironment infiltration at the single-cell spatial transcriptome level in ccRCC." (PMID 39882192, 2025). "The tumor inhibitory effects of SEL primarily depend on its ability to induce the nuclear retention of various cargo molecules that are transported by XPO1." (PMID 40229499, 2025). "Xpo1 inhibition (3 doses per week for two weeks) resulted in a greater than 95% decrease in tumor volume compared with a 4–12-fold increase in tumor size in vehicle control mice." (PMID 38302473, 2024). "Given this, targeting XPO1 with specific inhibitors presents a promising therapeutic strategy to restore normal transport dynamics, reduce oncogenic activity, and reinstate tumor-suppressor function." (PMID 39459201, 2024). "XPO1 has been shown to have an increased expression in several tumor cell types and has been validated as a target for cancer therapeutic interventions." (PMID 39132444, 2024). "Inhibition of XPO1 expression results in tumor cell growth inhibition in T-cell lymphoma cell lines in vitro." (PMID 38653804, 2024). "Xpo1 inhibition suppressed tumor proliferation and induced apoptosis as shown by phospho-histone H3 and cleaved caspase-3 staining, respectively." (PMID 38302473, 2024).